APLN (apelin)
Diseases named in the same sentence as APLN in open-access papers (continued):
Sharing a sentence is not in itself a finding about the gene and the disease.
cancer (continued). "It has also been noted that apelin expression was higher in vivo than in vitro, and the development of cancer cells was more intense in vivo, which may be explained by the use of endogenous, adipocyte-derived apelin for cancer cell metabolism." (PMID 37190027, 2023). "Apelin is a promising biomarker for the detection and prognosis of cancer." (PMID 36230579, 2022). "Results indicate the potential use of apelin as a biomarker for various cancers." (PMID 36230579, 2022). "It is critical to define the optimal cutoff points of serum apelin concentration indicating the presence of disease and its related processes to identify patients with cancer and implement treatment earlier, improving health-related outcomes and overall survival." (PMID 36230579, 2022). "There has been increased attention on apelin for cancer research since 1998." (PMID 36230579, 2022). "APLN/APLNR had been showed as prognostic markers in several types of cancers." (PMID 36193059, 2022). "More research will help understand the relationship between serum and tissue apelin; however, their uses in cancer may be unrelated." (PMID 36230579, 2022). "The role of apelin in cancer development and progression has been elucidated in recent years." (PMID 35574028, 2022). "However, while tumor tissue samples are often not readily available, serum samples are less invasive and potentially more helpful for measuring apelin concentration in many cases such as advanced cancers." (PMID 36230579, 2022). "Apelin has been shown to affect blood pressure and control the vascular tone in non-cancer cases." (PMID 36230579, 2022). "Additionally, not all studies reported statistically significant differences in apelin levels between patients with cancer and controls." (PMID 36230579, 2022). "It is unclear whether the relationship between serum apelin concentration and cancer cell proliferation and migration is similar to apelin found in tumor tissue." (PMID 36230579, 2022). "This review aims to synthesize evidence on the association of circulating apelin with cancer, illustrate gaps in knowledge, and discuss potential methodological improvement in the more sensitive assessment of apelin levels and innovative approaches for future cancer research." (PMID 36230579, 2022). "The 7 case–control and cohort studies did not measure apelin changes over time, so it is not clear if a causal relationship exists between serum apelin and the development of cancer." (PMID 36230579, 2022). "Furthermore, apelin expression inversely correlates with MuRF1 in muscle biopsies from cancer patients." (PMID 35406586, 2022). "Every study looked at differences in apelin between either cases and controls or different subtypes of cancer, showing that apelin may be of use in cancer diagnosis." (PMID 36230579, 2022). "Additionally, the DEGs enriched in the KEGG pathway were largely related to the MAPK signaling pathway, NOD-like receptor signaling pathway, microRNAs in cancer, and the apelin signaling pathway." (PMID 36505448, 2022). "Apelin as a protein plays a role in cancer development and may predict treatment response and prognosis; however, research is limited." (PMID 36230579, 2022). "KEGG analysis revealed that the top three terms with enriched unmethylated genes were the Oxytocin signaling pathway, Long-term depression, and Apelin signaling pathway, while those of methylated genes were the Pathways in cancer, Rap1 signaling pathway, and MAPK signaling pathway." (PMID 36199572, 2022). "It has been revealed that apelin/APJ may also play a role in mediating differentiation of mesenchymal stem cells to cancer stem cells." (PMID 33912466, 2021). "Moreover, apelin peptides are considered to be factors that stimulate tumor growth in several types of cancer, including gastric, ovarian, colon, hepatocellular, and oral squamous cell carcinoma." (PMID 34068679, 2021). "In several cancers, apelin could also protect cancer cells from apoptosis and increases cancer stability." (PMID 33912466, 2021).
cancer (continued). "A small number of hypoxia-associated genes (APLN, HIF1A, and BNIP3), cancer stem cell (CSC) markers (CD24 and CD44), hormonal regulation (HR) genes (ESR1, PGR, and TFF1), other selected genes (PPARGC1A, ILK), and HKGs (RPL32, GUSB, TBP, OAZ1 and NONO) were also included in the panel." (PMID 34206049, 2021). "By regulation of processes connected to cancer invasiveness, like cell migration, apoptosis, or angiogenesis, apelin may participate in the induction of metastasis." (PMID 34068679, 2021). "Other publications have reported that Apelin has tumor-promoting effects, but this disparity might be due to different tumor microenvironments depending on the cancer cell type used in the models." (PMID 34234274, 2021). "However, in our previous study, overexpression of Apelin greatly inhibited colon 26 tumor growth in mice after subcutaneous cancer inoculation by inducing tumor vascular maturation." (PMID 34234274, 2021). "Indeed, in a retrospective study, circulating levels of apelin were directly correlated with cancer stage in several different forms of tumors, including BC30." (PMID 33972642, 2021). "However, apelin infusion had a limited impact on the expression of different key genes involved in cancer cells proliferation, survival and energy metabolism." (PMID 32681609, 2020). "We can hypothesize that apelin could have a greater impact on tumour progression by activating proliferation of cancer cells with high Aplnr expression as suggested by one in vitro study performed with the MCF7 BC cell line with a high Aplnr expression." (PMID 32681609, 2020). "The clinical outcome of targeting APLN/APLNR pathway for cancer therapy depends on the tumor type." (PMID 31690961, 2020). "The expression of apelin has been found to be increased in many types of cancers, where it might act as a potentially proangiogenic factor." (PMID 32660156, 2020). "To date, not enough information has been published on the role of apelin in cancer-associated cachexia." (PMID 32660156, 2020). "The majority of the published data deal with the potential correlations between circulating leptin, adiponectin, and resistin levels with systemic inflammation and cachexia in obesity-related cancers, while data regarding resistin, visfatin, apelin are more limited." (PMID 32660156, 2020). "Apelin antagonists might also possess therapeutic potential themselves and recently there has been interest in their use for the treatment of cancer due to their anti-angiogenic effects." (PMID 31492821, 2019). "These important data provide a strong incentive to target Apelin in human cancer treatment." (PMID 31318171, 2019). "APLN has been reported to be involved in the regulation of cancer." (PMID 31410213, 2019). "In the survival analysis (n = 154, number of events: OS = 31, CSS = 21) APLN expression showed no prognostic association with either overall survival or cancer-specific survival." (PMID 30783205, 2019). "Moreover, we put forward an indication of apelin as a biomarker predicting cardiac diseases and various types of cancer." (PMID 29875677, 2018). "Additionally, in hepatocellular cell lines, upregulation of the APLN gene was identified as promoting angiogenesis, invasion, and metastasis of cancer cells." (PMID 29875677, 2018). "Additionally, using confocal microscopy, we noticed that apelin stimulated the proteolytic activity of cancer cells, especially increasing the level of membrane-type 1 matrix metalloprotease." (PMID 30127323, 2018). "This opposite effect in comparison to apelin treatment indicated that inhibition of apelin receptor and its downstream signalling may affect the capability of cancer cells to migrate." (PMID 30127323, 2018). "Increasing number amount of data also suggest, that that apelin might be a potential anti-cancer therapeutic target." (PMID 30127323, 2018).
cancer (continued). "Moreover, better understanding the process through which apelin regulates cancer development is still necessary to the creation of novel anti-cancer therapy." (PMID 30127323, 2018). "The level of the apelin peptide is elevated in several cancer types connected with adiposity." (PMID 29875677, 2018). "Many expression changes of the apelin/APJ system were observed in various types of cancer." (PMID 29875677, 2018). "In summary, apelin and its receptor are present in many types of cancer." (PMID 29875677, 2018). "Apelin might be involved in the regulation of tumor growth, cancer cell migration, neoangiogenesis, apoptosis suppression, and even metastasis induction." (PMID 29875677, 2018). "Many data indicate that in multiple cancer types, apelin and its receptor might be used as a prognostic biomarker." (PMID 29875677, 2018). "The level of plasma apelin-13 was also significantly higher in patients with this type of cancer." (PMID 29875677, 2018). "Furthermore, apelin has been suggested as a prognostic marker for cancer progression as its levels correlate with cancer invasion." (PMID 29188139, 2017). "Interestingly, they also described some preliminary data from an ongoing clinical trial, in which low APLN levels were observed in serum of cancer patients that respond well to bvz treatment." (PMID 28487489, 2017). "Recent studies show that Apelin was found to be up-regulated in a variety of human cancers." (PMID 27733135, 2016). "The aim of the present study was the investigation of (a) possible relationship between cancer cachexia and levels of serum adiponectin, apelin, and resistin and (b) correlation of serum adipocytokines with clinical, pathological, and blood parameters of cancer patients." (PMID 25049439, 2014). "Apelin has been shown as a potentially important proangiogenic factor in cancers." (PMID 25049439, 2014). "Consequently, the early identification and prevention of metastasis, whether through traditional treatments or interventions in the apelin/ apelin receptor interaction, emerge as crucial strategies in mitigating cancer-related pathologies and fatalities." (PMID 39962271, 2025). "Moreover, most of the differentially expressed miRNA genes are generally enriched in the Wnt signaling pathway, Apelin signaling pathway, and miRNA cancer pathway in the olfactory transduction, endocrine, and other mechanisms that regulate the calcium reabsorption pathway." (PMID 39794954, 2024). "In addition, Apelin can inhibit the apoptosis of cancer cells." (PMID 38881868, 2024). "Research suggested that APLN pathway has positive outcome on the cancer angiogenesis and disruption of this pathway could be effective for the antiangiogenic therapy in the therapeutic intervention of cancer." (PMID 38213742, 2024). "In several cancers, apelin may also protect cancer cells from apoptosis and may play a role in mediating differentiation of mesenchymal stem cells into cancer stem cells, whose self-renewal is facilitated by activating signaling pathways such as wnt/β-catenin and Jagged/Notch." (PMID 36902176, 2023). "Thus, the effect of apelin on the cancer cell itself is thought to be involved in tumor growth." (PMID 36776217, 2023). "Additionally, there are significant gaps in knowledge on the role of circulating apelin in cancer." (PMID 36230579, 2022). "Since the major apelin-producing organs, fat and muscles, are reduced during cancer cachexia, to understand whether the high levels of apelin in plasma could derive from tumors, we compared the protein content of apelin in tumors not causing cachexia, as 4T1, to tumors promoting cachexia, as C26." (PMID 35406586, 2022). "Through in silico, in vitro, and in vivo approaches and providing data on apelin expression in three distinct species (Rattus Norvegicus, Mus Musculus, and Homo sapiens), we noted apelin resistance in cancer cachexia and found that it may further exacerbate muscle loss." (PMID 35406586, 2022).
cancer (continued). "In addition, patients with various cancer diagnoses had higher apelin levels compared with HS." (PMID 36553076, 2022). "Apelin may play a role in cancer development by activating the apelin receptor, APJ." (PMID 36230579, 2022). "Besides, apelin/APJ signaling may play a critical role in cancer stem cells self-renew by activating signaling pathways like wnt/β-catenin and Jagged/Notch." (PMID 33912466, 2021). "It was revealed that apelin could promote cancer cell proliferation by increasing expression of factors involved in cell proliferation including cyclin D1, Ki-67, proliferating cell nuclear antigen (PCNA), and activating pathways like JAG1/Notch3, ERK1/2, and PI3K/Akt." (PMID 33912466, 2021). "This review reported the findings of adipokines (leptin, adiponectin, resistin, apelin, and visfatin) in cancer cachexia, highlighting that to study in-depth the involvement of these hormones in this pathology could lead to the development of new therapeutic strategies." (PMID 32660156, 2020). "Therefore, we wanted to explore whether combinations of Apelin blockade with current anti‐angiogenic therapies may be of therapeutic benefit in cancer." (PMID 31267692, 2019). "The effect of suppressing Apelin expression in cancer may however be dependent on the cancer type." (PMID 31318171, 2019). "Apelin could also be used as a predictive biomarker for other cancer therapies." (PMID 29875677, 2018). "Furthermore, apelin-13 induced ERK1/2 phosphorylation and autophagy inhibition, detected as an increase in microtubule-associated protein 1 light chain 3 alpha and beclin 1 levels, which both led to a proliferation of cancer cells." (PMID 29875677, 2018). "However, recent findings showed that apelin may be a possibly important proangiogenic factor in cancer." (PMID 30127323, 2018). "Thus, given the biological and clinical significance of apelin in the progression of human cancers, we hypothesized that it might enhance tumor progression by exerting a stimulatory effect on lymph vessel formation as well." (PMID 24962866, 2014). "Increased level of apelin in this type of cancer may correlate with tumor angiogenesis." (PMID 25049439, 2014). "Genes corresponding to the hypo-DMPs were also enriched in the pathways related to cancer progress (oxytocin signaling, GMP-protein kinase G (PKG) signaling, apelin signaling, and PI3K-Akt signaling)." (PMID 39858049, 2025). "This study found that plasma apelin levels increased one week after the cessation of PEMF therapy, potentially contributing to a more cancer-restrictive phenotype." (PMID 40072060, 2025). "Overactivation of apelin/APJ, which has been detected in many malignant tumors, and the strong correlation with progression-free and overall survival, suggested the role of an oncogene for the apelin gene." (PMID 40243599, 2025). "Previous studies have reported the expression of apelin and its receptor in endothelial cells, smooth muscle cells (SMC), and cancer cells." (PMID 39962271, 2025). "Comparative analysis of these protein expressions revealed higher levels of apelin and its receptor in endothelial and SMC cells compared to cancer cells." (PMID 39962271, 2025). "Therefore, targeting APLN/APLNR signalling pathway could be a promising strategy to treat cancer." (PMID 38213742, 2024). "Apelin expression is increased in different types of cancer, and the Apelin/APJ system plays a crucial role in tumor development by promoting cell proliferation, angiogenesis, metastasis, cancer stemness and drug resistance." (PMID 38881868, 2024). "Recent studies have indicated that the apelin (APL) signaling pathway is involved in various physiological and pathological processes, including cancer." (PMID 39684225, 2024). "Due to the vital role played by lysosomes in cancer, a LRRS signature was constructed, including 8 genes, namely, CLN3, GBA, CTSA, BSG, APLN, SORT1, ANXA2, and LAPTM4B." (PMID 38114725, 2023).
cancer (continued). "APLN/APLNR was reported to be involved in the regulation of tumor growth, cancer cell migration, neoangiogenesis, and apoptosis in different types of cancers." (PMID 36193059, 2022). "Apelin and APJ mRNAs are also enhanced in cancerous tissues and thought to play a role in promoting angiogenesis during cancer progression." (PMID 35406586, 2022). "The apelin/APJ axis primarily activates the ERK and PI3K/AKT signaling pathways, promoting cancer characteristics such as proliferation, migration, and invasion." (PMID 36291097, 2022). "Subsequently, functional enrichment analysis suggested that the mRNAs were primarily involved in kinase binding, transcription factor binding, transcriptional misregulation in cancer, regulation of TGF-β and apelin signaling pathway." (PMID 36200070, 2022). "This PDIN is associated with vital signaling pathways such as JAK-STAT, PI3K-Akt, cAMP, apelin, AGE-RAGE, hippo and processes such as cell cycle, transcriptional misregulation in cancer, fluid sheer stress." (PMID 34976314, 2022). "These growth factors have also been associated with other canonical pathways affected by HT, including “Apelin Cardiac Fibroblast Signaling Pathway” and “FAT10 Cancer Signaling Pathway”." (PMID 34836245, 2021). "Apelin, a ligand of the APJ receptor, is overexpressed in several human cancers and plays an important role in tumor angiogenesis and growth in various experimental systems." (PMID 33707612, 2021). "More studies should be carried out to get a better understanding of the function of apelin/APJ and Apela signaling in cancer." (PMID 33912466, 2021). "Potential mechanisms by which apelin/APJ and Apela mediate the regulation of cancer development and progression were also mentioned." (PMID 33912466, 2021). "Furthermore, an integrated analysis conducted to predict paracrine effectors in the KIRC cancer-to-stroma communication detected well-established soluble factors responsible for the hypoxia-related reaction and the so-far unestablished soluble factor, apelin (APLN)." (PMID 35079698, 2021). "In this article, we review the current studies focusing on the role of apelin/APJ signaling and Apela in different cancers." (PMID 33912466, 2021). "An integrated analysis of cancer and stroma transcriptome also detected putative paracrine signaling accelerators, such as the VEGFA, including a less-documented soluble factor, the APLN, in the KIRC pathology." (PMID 35079698, 2021). "Only 3 of the top 30 canonical pathways were predicted to be activated according to pathway analysis by IPA: T cell exhaustion, apelin endothelial signaling pathway, and PD-1, PDL1 cancer immunotherapy pathway." (PMID 32636844, 2020). "Thus, in a controlled model of VEGF‐induced angiogenesis, Apelin and VEGF induce similar downstream pathways and genes relevant for endothelial cell proliferation and blood vessel sprouting, suggesting that Apelin inhibition could complement and potentiate current anti‐angiogenic cancer treatment." (PMID 31267692, 2019). "Cancer accounts for only 3.3% of total diseases related to selected myokines (apelin, BDNF, IL-15, irisin, SPARC), but additional myokines have been shown to be more clearly involved in cancer cachexia." (PMID 30984014, 2019). "Cancer-related genes MUC1, FN1, and S100-family members were the most clinically relevant in CPTC, while APLN and IL16, both immune-related, were clinically relevant in FVPTC." (PMID 31443155, 2019). "TCGA pan-cancer analysis further revealed that up-regulation of APLN is the most profound in HCC among other common cancers, indicating its importance in this specific cancer type." (PMID 31410213, 2019). "Many results suggest that the apelin/APJ system is involved in regulation of the proliferation, migration, and invasion abilities of cancer cells, leading to metastasis." (PMID 29875677, 2018).